ATG7 (autophagy related 7)
Diseases named in the same sentence as ATG7 in open-access papers (continued):
Sharing a sentence is not in itself a finding about the gene and the disease.
infection (continued). "Steady-state mRNA of both Atg7 and LC3B were significantly increased (up to sixfold increase) in macrophages transfected with siRNA-Lpg2936 during the infection period in comparison with control-transfected macrophages, which revealed a sustained level of these mRNAs at the indicated time points." (PMID 32064256, 2019). "Silencing ATG7 did not significantly affect bacterial load or DC death during the 2h of infection with flagellin-expressing STm." (PMID 29253868, 2017). "ATG7 silencing did not affect priming, as shown by the lack of effect in either WT or pearl DCs on TNFα secretion after STm infection or on pro-IL-1β production after stimulation with LPS-beads." (PMID 29253868, 2017). "Unlike atg5 and atg7 mutants, nbr1 mutants were normal in age- and dark-induced senescence and in response to necrotrophic pathogen infection." (PMID 23341779, 2013). "However, when compared with ATG7 KO macrophages, the replication and cell death phenotype in iPSDM lacking ATG14 was more pronounced at 96 h post infection (30% ATG7 KO versus 50% in ATG14 KO cell death after 96 h infection)." (PMID 36959508, 2023). "However, H3K27me3 was not enriched at either Atg5 or Atg7 promoters under similar infection conditions." (PMID 34381738, 2021). "We found that broad-spectrum antibiotics supplementation could partially rescue the death of Atg7-/-;Stk11-/- mice, but not Stk11-/- mice, suggesting the role of autophagy in preventing infection-related death." (PMID 33236987, 2020). "Notably, targeting of Lpg2936 by RNAi restored the expression of autophagy-related genes Atg7 and LC3B during infection and increased the protein level of the Atg5–Atg12 complex, unconjugated LC3-I, and conjugated LC3II proteins when compared to control-transfected and -infected macrophages." (PMID 32064256, 2019). "However, inhibiting either pathway by RNAi against Dronc, Death-associated APAF1-related killer (Dark), Atg1, Atg7 or Atg18, or by overexpression of the caspase inhibitor P35 (UAS-P35), had no significant negative effect on upd3-lacZ levels during infection." (PMID 29108021, 2017). "It should be noted that during the course of the respective antigen presentation experiments (48 hpi), siRNA-mediated silencing of Beclin-1 and Atg7 did not affect expression and/or infection-dependent induction of surface MHC I (H-2Kb and H-2Db), CD80, CD86, PD-L1 or PD-L2." (PMID 28634388, 2017). "Interestingly, although IFN β, IL6 and IP10 mRNA production are almost equivalent at 8 hours post-infection when comparing infected and non-infected cells, the levels were significantly higher in Atg5 and Atg7 knock-down cells relative to control cells." (PMID 23320079, 2013). "In response to infection with H37Rv (L4), as a reference strain, the expression of ATG 16L1, ATG7, and LAMP1 genes decreased (p < 0.05), while no changes were observed in the expression of other genes." (PMID 36000264, 2022). "Whereas infection of control THP-1 macrophages with HIV-1 CA P90A increases the expression of IFNB1, this effect is not seen in ULK1, BECN1, or ATG7 knockout THP-1 cells." (PMID 33052966, 2020). "Huh7 infection by HCVpp was not altered in cells treated with siRNA against LC3, ATG7 or ATG12, thus suggesting that neither LC3 nor the ATG5-12 conjugate is involved in viral entry." (PMID 28067309, 2017). "The requirement of autophagy-initiation proteins ULK1, Beclin 1, and ATG14L and PI3-kinase activity but not elongation proteins ATG5, ATG16L1, ATG4B, ATG7, and LC3B suggested Brucella selectively co-opts autophagy-initiation complexes to subvert host clearance and promote infection." (PMID 38376367, 2024). "Furthermore, a constructed Lpg2936 segment in the GFP expression vector was translocated in the host nucleus and successfully induced methyladenine changes in Atg7 and LC3B promoter region and subsequently regulated autophagy in A549 cells independent of infection." (PMID 32064256, 2019).
neurodegenerative disease (16 papers, 2008 to 2026). A disorder of the central nervous system characterized by gradual and progressive loss of neural tissue and neurologic function. "For instance, the loss of autophagy-related genes like Atg7 in microglia leads to increased production of inflammatory mediators and exacerbates neuroinflammation in models of neurodegenerative diseases like PD and AD." (PMID 41277110, 2026). "In contrast to the prevalent relevance of the DEGs found in the lncRNA data, little is known about the roles of these genes in reward mechanisms, although both Atg7 and Prkca have been associated with neurodegenerative diseases." (PMID 39857659, 2024). "Polymorphisms in the ATG genes, including ATG5 and ATG7, have been associated with an early onset of neurodegenerative diseases, including HD." (PMID 31941072, 2020). "The Purkinje cell-specific Atg7 knockout obstructed autophagy-related membrane trafficking and turnover, which led to axonal dystrophy associated with neurodegenerative disease." (PMID 31749688, 2019). "Similar to nestin-Atg7−/− mice, Purkinje cell-specific loss of Atg7 function impeded autophagy-related membrane trafficking and turnover resulting in axonal dystrophy, a sign of axonopathy associated with neurodegenerative disease." (PMID 26404030, 2015). "Mice deficient in either Atg5 or Atg7 in the CNS develop progressive behavioral and motor deficits typically associated with neurodegenerative diseases." (PMID 26503303, 2015). "Variants of ATG7 in neurodegenerative diseases reduce autophagic activity." (PMID 41277110, 2026). "Within the context of AD and other neurodegenerative diseases, ATG7 is required during autophagy for autophagosome assembly." (PMID 37728850, 2024). "Experimental evidence showed that down-regulation of autophagy-related genes, Atg5 or Atg7, in the CNS lead to the aggregation of poly-ubiquitinated protein debris in neurodegenerative disease animal models." (PMID 37181621, 2023). "Inhibition of basal autophagy in vivo following Atg5 or Atg7 deletion results in the accumulation of ubiquitinated protein aggregates leading to cytotoxicity and neurodegenerative disease, highlighting the critical cytoprotective role of basal autophagy." (PMID 35968799, 2022). "In addition, ATG7, an autophagy-related gene, plays a critical role in autophagy induction and the progression of neurodegenerative disease." (PMID 32158393, 2020).
bacterial infection (6 papers, 2018 to 2021). "Atg7 linked the immune cross-talk between autophagy and pyroptosis pathways in bacterial infection, particularly in P. aeruginosa-induced septic progression." (PMID 29706799, 2018). "ATG7 plays a crucial role in the inflammatory response to bacterial infection." (PMID 34321587, 2021). "H3K9me2/3 was significantly enriched at the promoter regions of both Atg5 (P ≤ 0.01) and Atg7 (P ≤ 0.001) in response to MtbPrt bacterial infection, while no such enrichment was observed in uninfected and MsmpSMT3-infected cells." (PMID 34381738, 2021).
cardiovascular disease (6 papers, 2018 to 2025). "Therefore, deficient or excessive ATG7 may interfere with inflammation, cell proliferation, and apoptosis, contributing to the development of cardiovascular diseases through its non‐autophagic function." (PMID 30407747, 2018). "By using both pharmacological and genetic approaches, including CRISPR-mediated knockout of ATG5 and ATG7, this study provides robust evidence that autophagy is a critical determinant of cholesterol homeostasis, offering new insights with potential therapeutic relevance for cardiovascular disease." (PMID 41343507, 2025).
adenocarcinoma (5 papers, 2019 to 2024). A common cancer characterized by the presence of malignant glandular cells. "AM-101 in vitro enhances ATG7 protein levels in both patient-derived adenocarcinoma primary (H1792) and brain-metastatic (UW-lung-16) cells." (PMID 39335139, 2024). "In the TMA, Atg7 expression was found to be significantly upregulated (p < 0.01), whereas Beclin-1 expression was significantly decreased in adenocarcinomas compared to (not matched) normal mucosa (p < 0.001)." (PMID 32046105, 2020).
inflammation (5 papers, 2021 to 2023). Aberrant reaction of the microcirculation characterized by movement of fluid and leukocytes from the blood into extravascular tissues. "Mice with autophagy deficiency (Atg5−/− and Atg7−/−) develop spontaneous sterile lung inflammation." (PMID 35057008, 2022). "Similarly, other investigators using myeloid-specific Atg7-deficient mice demonstrated spontaneous pulmonary inflammation, elevated expression of Tnfα, Il6, Ccl2, Cxcl1, Cxcl2 genes, and myeloid cell infiltration in the lung." (PMID 34204710, 2021). "Specifically, we found higher ATG7 mRNA and ATG7 protein expression in women with mild lobular inflammation than in those without it." (PMID 36674839, 2023).
neurodevelopmental disorder (5 papers, 2019 to 2025). A behavioral and cognitive disorder with onset during the developmental period that involves impaired or aberrant development of intellectual, motor, or social functions. "In humans, recessive variants causing severe loss of the ATG7 enzyme, lead to neurodevelopmental disorders affecting the brain and muscle, with more subtle evidence of endocrine hypofunction also present in these individuals." (PMID 39944686, 2025). "A most recent study has identified recessive and loss-of-function mutations in both ATG7 alleles in patients with neurodevelopmental disorders in five unrelated families." (PMID 34920755, 2021). "The causal link of autophagy impairment to neurodevelopmental disorders is highlighted by a recent report of deleterious, recessive variants of ATG7 in human." (PMID 34920755, 2021). "Among these, haploinsufficiency ofSETD5, BRPF1, CRBN, ATG7, SLC6A11, GRM7, and ARPC4has been linked to neurodevelopmental disorders and cognitiveimpairment." (PMID 40995453, 2025).
myopathy (4 papers, 2012 to 2023). A disease of the muscle in which the muscle fibers do not function properly. "Knockdown of Atg7 leads to myopathy, misalignment of the A and Z bands, and increased numbers of mitochondria with membranous structures and protein aggregates." (PMID 37470707, 2023). "The block in autophagy causes disorganized sarcomeres, myofiber degeneration, and accumulation of polyubiquitinated proteins that manifest in the form of severe muscle weakness and myopathy in the Atg7−/− mice." (PMID 28122601, 2017).
neurological diseases (4 papers, 2019 to 2025). "Specifically, genes such as ATG16L1, ATG5, ATG10 or ATG7, accumulate multiple SNPs linked to pathologies that include cancer, neurological disorders, or inflammatory bowel diseases." (PMID 33147747, 2020). "Atg7 is essential for autophagy initiation and has been implicated in neurological disorders." (PMID 39253496, 2025). "A clinical study found ATG7 variants in neurological diseases, and it has been suggested that changes in ATG7 protein expression and polymorphisms in ATG genes are associated with aberrant autophagy activity and contribute to the pathological processes of these diseases." (PMID 31749688, 2019).
kidney disease (3 papers, 2023 to 2025). "Consistently, studies in mouse models have demonstrated that reduced function of ULK1, ATG5 or ATG7 in kidney cells is closely associated with various kidney diseases, including DKD59,60." (PMID 41131336, 2025). "In summary, the present study provides novel evidence of intense p-S6 staining in TLTs in four kidney disease models: aged wild-type mice, aged Atg7−/− mice, Pkd1RC/RC mice, and ischemic kidneys." (PMID 40496859, 2025). "We were intrigued by the large amount of p-S6 seen in the TLTs and surrounding tubules in Atg7−/− kidneys, so next we determined the role of mTOR in TLT development and growth in two separate models of kidney disease, ADPKD and renal ischemia." (PMID 40496859, 2025).
heart disease (2 papers, 2019 to 2024). "MiR-542-5p might also be a target for treating heart disease caused by hypoxia/reoxygenation-induced cardiomyocyte injury due to its relationship with Atg7 mRNA73." (PMID 38553562, 2024). "Several miRNAs have Inhibitory effects on Atg7 in heart disease." (PMID 38553562, 2024). "miR-27a-5p upregulation attenuated hypoxia-induced cardiomyocyte injury by regulating autophagy and apoptosis via Atg7, suggesting that miR-27a-5p may be a novel treatment strategy for hypoxia-related heart diseases." (PMID 31100777, 2019). "More deeply, we revealed the miR-27a-5p-Atg7 interaction in vivo and in vitro, and functionally, miR-27a-5p attenuated hypoxia-induced cardiomyocyte injury by regulating autophagy and apoptosis via Atg7, which further confirmed the crucial roles of miRNA-23a-27a-24 cluster in heart diseases." (PMID 31100777, 2019).
colorectal (1 paper, 2020). "Additionally, a recent report discovered a major role of the central autophagy protein Atg7 in the prevention of dysbiosis-induced colorectal tumorigenesis." (PMID 32046105, 2020).
intestinal disease (1 paper, 2019). "The knockout of ATG7 in intestinal epithelial cells of mice synergistically intensified the intestinal disease, increased widespread submucosal inflammation, and inhibited the secretion of intestinal mucins." (PMID 31683886, 2019).
vascular disorder (1 paper, 2018). A general term used to describe any disease affecting blood vessels]. "The relevance of autophagy in vascular disorders is also supported by previous studies showing that there is thickened aortic media along with cellular hypertrophy in VMSC-specific Atg7 knockout mice." (PMID 29463847, 2018).
ATG7 also shares sentences with these, for which no sentence is quoted: acute myocardial infarction (6 papers); frontotemporal dementia (4); aortic aneurysm (2); chronic pancreatitis (2); developmental delay (2); diabetes nephropathy (2); gastric adenocarcinoma (2); Impaired glucose tolerance (2); Intellectual disability (2); knee osteoarthritis (2); nasopharyngeal carcinoma (2); proteinopathy (2); type 2 diabetes mellitus (2); Ureteral obstruction (2); uveal melanoma (2); acute lung injury (1); allergic asthma (1); amyloid (1); anaplastic astrocytoma (1); angiosarcoma (1); Aortic dissection (1); autoimmune disease (1); Azoospermia (1); benign brain tumour (1); benign oncocytoma (1); benign tumor (1); brain disorder (1); Candidemia (1); cataract (1); cerebellar ataxia (1).
A further 58 diseases each share a sentence with ATG7 in 1 paper.